DARS2 (aspartyl-tRNA synthetase 2, mitochondrial)
Description:
Catalyzes the attachment of aspartate to tRNA(Asp) in a two-step reaction: aspartate is first activated by ATP to form Asp-AMP and then transferred to the acceptor end of tRNA(Asp).
Synonyms: AspRS; FLJ10514; mtAspRS; CMT2LL; LBSL; MT-ASPRS
Tractability: PROTAC: ubiquitination databases record sites on it; its protein half-life has been measured.
Gene: Protein-coding gene on chromosome 1 (173,824,540 to 173,858,808, forward strand). Ensembl gene ENSG00000117593.
Subcellular location: Mitochondrion matrix; Mitochondrion membrane
Subcellular location (Human Protein Atlas): Mitochondria; Nucleoplasm
Pathways (Reactome):
Metabolism of proteins: Mitochondrial tRNA aminoacylation
Gene Ontology:
Molecular function: aspartate-tRNA ligase activity; aspartate-tRNA(Asn) ligase activity; protein binding; protein homodimerization activity; ATP binding; tRNA binding; aminoacyl-tRNA ligase activity; ligase activity; nucleic acid binding; nucleotide binding
Biological process: mitochondrial asparaginyl-tRNA aminoacylation; tRNA aminoacylation; aspartyl-tRNA aminoacylation; tRNA aminoacylation for protein translation
Cellular component: mitochondrial matrix; mitochondrial membrane; mitochondrion; cytoplasm
Genetic constraint (gnomAD): Loss-of-function variants: 50 observed, 68.55 expected, observed/expected ratio (o/e) 0.73, 90% interval 0.58 to 0.92. The upper end of that interval is the gene's LOEUF score, 0.92, which puts it in group 3 of 6, group 1 being the genes least tolerant of losing a copy. Missense variants: 588 observed, 690.5 expected, observed/expected ratio (o/e) 0.85, 90% interval 0.8 to 0.91. Synonymous variants: 215 observed, 244.82 expected, observed/expected ratio (o/e) 0.88, 90% interval 0.79 to 0.98.
Gene-disease validity (ClinGen):
ClinGen rates the evidence that DARS2 causes each of these diseases.
mitochondrial disease (autosomal recessive): Definitive.
Homologues: Orthologues: chimpanzee DARS2 (99% identical), macaque DARS2 (97% identical), pig DARS2 (87% identical), rabbit DARS2 (87% identical), dog DARS2 (86% identical), guinea pig DARS2 (86% identical), mouse Dars2 (85% identical), rat Dars2 (85% identical), tropical clawed frog dars2 (64% identical), zebrafish dars2 (61% identical), Drosophila melanogaster AspRS-m (46% identical), Caenorhabditis elegans dars-2 (40% identical). Paralogues in human: DARS1 (18% identical), KARS1 (18% identical), NARS1 (18% identical), NARS2 (16% identical).
Diseases named in the same sentence as DARS2 in open-access papers:
DARS2 is named in the same sentence as 57 diseases in open-access papers, as found by Europe PMC text mining. Sharing a sentence is not in itself a finding about the gene and the disease. The quoted sentences say what the papers report.
Leukoencephalopathy (35 papers, 2011 to 2025). This term describes abnormality of the white matter of the cerebrum resulting from damage to the myelin sheaths of nerve cells. "As already mentioned, DARS2 mutations can determine leukoencephalopathy with brainstem and spinal cord involvement and lactate elevation (LBSL)." (PMID 35203288, 2022). "Several clinical studies have shown that mutations in DARS2 are associated with leukoencephalopathy." (PMID 29052520, 2017). "Leukoencephalopathy with brain stem and spinal cord involvement is caused by mutations in the DARS2 gene, which encodes a mitochondrial aspartyl-tRNA synthetase." (PMID 23531239, 2013). "Mitochondrial aspartyl-tRNA synthetase (DARS2) mutations cause leukoencephalopathy with brain stem and spinal cord involvement and lactate elevation (LBSL)." (PMID 21749694, 2011). "DARS2 is genetically linked to leukoencephalopathy with brain stem and spinal cord involvement." (PMID 37034680, 2023). "Mutations in the DARS2 gene are associated with leukoencephalopathy (LBSL)." (PMID 29052520, 2017). "DARS2-related leukoencephalopathy, also called Leukoencephalopathy with Brainstem and Spinal cord involvement and Lactate elevation (LBSL), is a rare neurological disorder with a wide phenotypic spectrum." (PMID 36909591, 2023). "Leukoencephalopathy with brainstem and spinal cord involvement and lactate elevation (LBSL) is a rare neurological disorder caused by the mutations in the DARS2 gene, which encodes the mitochondrial aspartyl-tRNA synthetase." (PMID 37563224, 2023). "Leukoencephalopathy with brain stem and spinal cord involvement and lactate elevation (MIM# 611105) is caused by biallelic pathogenic variants in the DARS2 gene, that encodes the mitochondrial aspartyl-transfer RNA synthetase." (PMID 37564735, 2023). "The first Mendelian disease reported to be caused by mt-ARS mutations was leukoencephalopathy with brain stem and spinal cord involvement and lactate elevation (MIM #611105) due to autosomal recessive pathogenic variants in DARS2, which was reported in 2007." (PMID 33426504, 2020). "Leukoencephalopathy with brainstem and spinal cord involvement and lactate elevation (LBSL) is a disease caused by a range of mutations in the DARS2 gene, initially identified in 2003." (PMID 33574740, 2020). "Leukoencephalopathy with brainstem and spinal cord involvement and lactate elevation (LBSL) is a leukodystrophy caused by mutations in the DARS2 gene which encodes mitochondrial aspartyl-tRNA synthetase." (PMID 31671122, 2019). "Mutations in DARS2 and EARS2 result in very characteristic MRI phenotypes of leukoencephalopathy with brainstem and spinal cord involvement and lactate elevation (LBSL) and leukoencephalopathy with thalamus and brainstem involvement and high lactate (LTBL)." (PMID 29980628, 2018). "While DARS2 mutations are linked to childhood-to-adolescence-onset leukoencephalopathy affecting the brain and spinal cord, no enrichment has been found in MS patients." (PMID 40234289, 2025). "For instance, mutations in the mitochondrial aspartyl‐tRNA synthetase, DARS2 (MIM 610956), can lead to leukoencephalopathy, while dysfunctional leucyl‐tRNA synthetase, LARS2 (MIM 604544), has been linked to several pathogenic conditions including infertility and hearing loss." (PMID 30920170, 2019). "Genes other than DARS2 may be involved in Rottweiler leukoencephalomyelopathy and may also be relevant in human leukoencephalopathy with brain stem and spinal cord involvement." (PMID 23531239, 2013). "For instance, mutations in DARS2 and EARS2 are associated with leukoencephalopathy, not necessarily seen in the clinical presentations of patients with other ARS2 variants." (PMID 30920170, 2019). "Leukoencephalopathy may be seen with AARS2, DARS2, EARS2, NARS2, PARS2, and WARS2 disorders." (PMID 33426504, 2020).
hepatocellular carcinoma (8 papers, 2017 to 2024). A malignant tumor that arises from hepatocytes. "The first report on the relationship between DARS2 and cancer was in 2017, in which it was reported that DARS2 can promote the development of hepatocellular carcinoma by accelerating the cell cycle and reducing apoptosis." (PMID 34996932, 2022). "As for the DARS2 gene, its abnormal expression is reportedly involved in the occurrence and development of primary liver carcinoma, with the expression level being closely related to the tumor size, stage, and prognosis." (PMID 36411477, 2022). "DARS2 promoted cell cycle progression and inhibited hepatocellular carcinoma cell apoptosis via the miR-30e-5p/MAPK/NFAT5 pathway." (PMID 33685397, 2021). "Our results showed that HBV suppressed NFAT5 expression by inducing hypermethylation of the AP1-binding site in the NFAT5 promoter and inhibiting miR-30e-5p/MAP4K4/DARS2 pathway in hepatoma cells." (PMID 29052520, 2017). "The results indicated that DARS2 mRNA and protein expression was higher in hepatoma cell lines than in L02 cells." (PMID 29052520, 2017). "We next examined DARS2 expression in hepatoma cell lines, including Hep3B, HepG2, SK-Hep-1 and Huh7 cells, and the human embryonic liver cell line L02." (PMID 29052520, 2017). "We next found that NFAT5 negatively regulated DARS2, and the inhibition of tumorigenesis by NFAT5 on was executed through DARS2 in different hepatoma cell lines." (PMID 29052520, 2017). "In addition to its known contribution to LBSL, DARS2 has been implicated as an oncogene in hepatocellular carcinoma and lung adenocarcinoma." (PMID 39039092, 2024). "Our results showed that HBV could suppressed NFAT5 expression by inducing hypermethylation of the AP1-binding site in the NFAT5 promoter and inhibiting miR-30e-5p/MAP4K4/DARS2 pathway in hepatoma cells." (PMID 29052520, 2017). "It has been found that DARS2 is an oncogene in hepatocellular carcinoma and can promote the progression of the hepatocellular carcinoma cell cycle while inhibiting apoptosis in HCC cells." (PMID 38299141, 2023). "DARS2 has been identified as a hepatocellular carcinoma (HCC) oncogene that promotes HCC cell cycle progression and inhibits HCC cell apoptosis." (PMID 36275774, 2022). "Hence, we investigated whether the effect of NFAT5 on cell apoptosis and the cell cycle would be hindered by altering DARS2 expression in hepatoma cells to verify our hypothesis." (PMID 29052520, 2017). "The results showed that cyclin D1 protein expression was reduced after knockdown of DARS2 compared with expression in the negative control group, which indicated that DARS2 accelerated cell cycle progression in hepatoma cells." (PMID 29052520, 2017).
leukodystrophy (7 papers, 2018 to 2025). Leukodystrophies are a group of rare, progressive, metabolic, genetic diseases that affect the brain, spinal cord and often the peripheral nerves. "It is interesting to note that the presence of cerebral WM and spinal cord signal abnormalities is a pretty rare association of neuroradiological features and it is typically observed in other aaRSs deficiencies, notably in DARS and DARS2 related leukodystrophies." (PMID 29615062, 2018). "LysRS are involved in myelin formation and defects in other ARSes (e.g., AARS2, DARS2, EARS2, and LARS2) have been found to be responsible for leukodystrophy." (PMID 33942428, 2021).
lung adenocarcinoma (6 papers, 2022 to 2024). A carcinoma that arises from the lung and is characterized by the presence of malignant glandular epithelial cells. "Our study also showed that with an increased expression of DARS2, the death risk of patients with lung adenocarcinoma gradually elevated." (PMID 34996932, 2022). "Moreover, DARS2 overexpression was associated with poor prognosis in lung adenocarcinoma." (PMID 38299141, 2023). "The enzyme Aspartyl tRNA synthetase 2 (DARS2) is a mitochondrial enzyme, and previous studies have reported its crucial role in the development of bladder cancer, lung adenocarcinoma, ovarian cancer, and hepatocarcinogenesis." (PMID 38382106, 2024). "It reported an upregulation of DARS2 expression in lung adenocarcinoma and highlighted its role in regulating the proliferation, invasion, and apoptosis of lung adenocarcinoma cells." (PMID 38299141, 2023). "We infer that DARS2 also affects the prognosis of lung adenocarcinoma by accelerating cell cycle progression and attenuating cell apoptosis, but further research is necessary to verify its function." (PMID 34996932, 2022). "In lung adenocarcinoma cells, DARS2 is involved in proliferation, invasion, and apoptosis and shows promise as a therapeutic target." (PMID 36275774, 2022). "The mRNA level of DARS2 was significantly elevated in lung adenocarcinoma samples compared with normal lung samples (P < 0.001)." (PMID 34996932, 2022). "In addition, DARS2 is upregulated in bladder cancer, lung adenocarcinoma, ovarian cancer, and hepatocarcinogenesis." (PMID 38382106, 2024). "It suggests that DARS2 may be proposed as a new biomarker to distinguish between multiple myeloma and lung adenocarcinoma." (PMID 38299141, 2023). "CTPS2 and DARS2 are new signatures affecting the prognosis of lung adenocarcinoma and may be potential new treatment targets." (PMID 34996932, 2022). "Interestingly, we also found that CTPS2 and DARS2 which never be reported were associated with the increasing death risk of lung adenocarcinoma." (PMID 34996932, 2022). "This study investigated the correlation between the expression of DARS2 and metabolic parameters of 18F-FDG PET/CT, and explored the potential mechanisms of DARS2 affecting the proliferation and glycolysis of lung adenocarcinoma (LUAD) cells." (PMID 37626419, 2023). "Liu and colleagues discovered that DARS2 can serve as a prognostic marker for non-adenocarcinomas and promote the proliferation, invasion, and migration of lung adenocarcinoma cells while inhibiting cell apoptosis." (PMID 38299141, 2023). "The relationship between CTPS2 and DARS2 and the prognosis of lung adenocarcinoma has not been studied." (PMID 34996932, 2022).
Ataxia (4 papers, 2014 to 2024). Ataxia refers to impaired coordination of voluntary muscle movement. "Another patient with homozygous DARS2 mutations experienced episodic bouts of ataxia that were induced by exercise, a highly unique disease presentation that has not been described in another LBSL patient." (PMID 33574740, 2020). "Moreover, compound heterozygous mutations in AARS2 and DARS2 were detected in two male patients with slowly progressive ataxia and peripheral neuropathy." (PMID 37237429, 2023). "DARS2 is indispensable for Purkinje cell survival and protects against cerebellar ataxia." (PMID 38779771, 2024).
bladder cancer (4 papers, 2022 to 2025). "We found DARS2 to be upregulated in bladder cancer, associated with tumor progression and poor prognosis." (PMID 38299141, 2023). "Targeting DARS2 and its regulation of mitophagy is a promising therapeutic strategy to improve the outcomes for patients with bladder cancer." (PMID 39990673, 2025). "The observations from this study have provided novel insights into the multifaceted roles of DARS2-mediated mitophagy in bladder cancer." (PMID 39990673, 2025). "We analyzed the correlation between DARS2 expression and prognosis, tumor stage, and immune infiltration in bladder cancer using The Cancer Genome Atlas (TCGA) database." (PMID 38299141, 2023). "Immunohistochemical (IHC) analysis of the ten pairs of bladder cancer tissues indicated a heightened expression of DARS2 in bladder cancer compared to normal bladder mucosal epithelial tissues (P<0.05)." (PMID 38299141, 2023). "Secondly, we delved into the impact of DARS2 on the biological functions of bladder cancer cells, establishing a connection between DARS2 expression and an immunosuppressive tumor microenvironment, including its correlation with PD-L1 expression." (PMID 38299141, 2023). "In addition, we conducted an overexpression experiment of DARS2 in bladder cancer cells and assessed relevant indicators." (PMID 38299141, 2023). "In order to further study the impact of DARS2 on bladder cancer, we used T24 cells to conduct tumorigenesis experiments in nude mice.we found that T24 cells with DARS2 knockdown formed smaller subcutaneous tumors in nude mice compared to the NC group in animal experiments." (PMID 38299141, 2023). "Additionally, we observed that high-grade bladder cancer exhibited elevated levels of DARS2 expression compared to low-grade bladder cancer." (PMID 38299141, 2023). "As such, DARS2 can be used as a prognostic marker for bladder cancer." (PMID 36685927, 2022). "However, the biological role of DARS2 in bladder cancer remains elusive." (PMID 38299141, 2023).
cardiomyopathy (3 papers, 2018 to 2024). A disease of the heart muscle or myocardium proper. "The deletion of Clpp in the hearts of DARS2-deficient animals contributes to the development of cardiomyopathy." (PMID 39273594, 2024). "Thus, cardiomyopathy, which is the result of the loss of Dars2 (mitochondrial aspartyl-tRNA synthetase 2), presents impaired mitochondrial proteostasis and mitochondrial oxidative phosphorylation (OXPHOS) system in the heart and the induction of the UPRmt." (PMID 35328371, 2022). "A heart and skeletal muscle-specific aspartyl-tRNA synthetase 2 (Dars2) knockout (Dars2-KOCkmm) mouse with fatal cardiomyopathy has been reported." (PMID 30566859, 2018).
Mitochondrial encephalopathy (2 papers, 2023 to 2025). "In Dars2-deficient mouse models of mitochondrial encephalopathy, ClpP ablation preserved neuronal integrity, improved OXPHOS, and stabilized respiratory complex I and its supercomplexes." (PMID 41155556, 2025).
ovarian carcinoma (2 papers, 2023 to 2024). A malignant neoplasm originating from the surface ovarian epithelium. "This correlation was not clear with the ovarian cancer cell lines with low-OXPHOS subunit expression; specifically, the OVCAR-8 cells had normal levels and, in some cases, higher levels of PGC1α, TFAM, TUFM, and DARS2 protein expression." (PMID 36937395, 2023).
bacterial pneumonia (1 paper, 2024). Acute infection of the lung parenchyma caused by bacteria (e.g., Streptococcus pneumoniae, Haemophilus influenzae, Chlamydia pneumoniae, Mycoplasma pneumoniae, and Legionella pneumophila). "We describe a mitochondrial protein, aspartyl-tRNA synthetase (DARS2), which is released in circulation during bacterial pneumonia in humans and displays intrinsic innate immune properties and cellular repair properties." (PMID 39039092, 2024). "Thus, DARS2 is secreted in plasma during humans with bacterial pneumonia, perhaps as a compensatory response, where it elicits host protective immunostimulatory effects." (PMID 39039092, 2024).
cervical cancer (1 paper, 2021). A primary or metastatic malignant neoplasm involving the cervix. "RPP25, BARD1, BRCA1, CD3EAP, CSTF2, DARS2 and DNMT3B was up-regulated in most of cervical cancer tissues compared with corresponding normal cervix tissues." (PMID 34863153, 2021).
developmental delay (1 paper, 2019). "Siblings with DARS2 deficiency presented with global developmental delay within the first year of life." (PMID 32071833, 2019).
Encephalopathy (1 paper, 2014). Encephalopathy is a term that means brain disease, damage, or malfunction. "The first patients with splice-site mutation in either DARS2 or RARS2 presented with encephalopathy." (PMID 24639874, 2014).
esophageal cancer (1 paper, 2024). A primary or metastatic malignant neoplasm involving the esophagus. "Through analysis of the TCGA database, we found that DARS2 was significantly higher in esophageal cancer samples than in the control group." (PMID 38382106, 2024). "The results of cell experiments revealed that the expression of DARS2 was significantly increased in human esophageal cancer cell lines compared to human normal esophageal epithelial cells." (PMID 38382106, 2024).
lymph node metastasis (1 paper, 2024). "Upregulation of DARS2 could be related to Tumor-Node-Metastasis (TNM) stage, high lymph node metastasis, and inferior prognosis." (PMID 38361754, 2024).
Nystagmus (1 paper, 2020). Rhythmic, involuntary oscillations of one or both eyes related to abnormality in fixation, conjugate gaze, or vestibular mechanisms. "Three siblings with LBSL who presented with nystagmus, slurring of speech, muscle tonus abnormality, ataxic gait, hypo or hyperreflexia, tremor, and mental retardation caused by DARS2 mutation were considered to display a severe form of LBSL." (PMID 33182419, 2020).
pneumonia (1 paper, 2024). An acute, acute and chronic, or chronic inflammation focally or diffusely affecting the lung parenchyma, caused by an infection in one or both of the lungs (by bacteria, viruses, fungi, or mycoplasma.). "Further studies examining the kinetics of FBXO24 expression and DARS2 abundance in experimental pneumonia and in humans will elucidate the biological association for these proteins in host immunity." (PMID 39039092, 2024). "During experimental pneumonia, Fbxo24 knockout mice exhibit elevated DARS2 levels with an increase in pulmonary cellular and cytokine levels." (PMID 39039092, 2024). "However, the biological relevance of DARS2 in experimental pneumonia is unknown." (PMID 39039092, 2024).